CYP2C19 (cytochrome P450 family 2 subfamily C member 19)
Diseases named in the same sentence as CYP2C19 in open-access papers (continued):
Sharing a sentence is not in itself a finding about the gene and the disease.
injury (1 paper, 2021). Damage inflicted on the body as the direct or indirect result of an external force, with or without disruption of structural continuity. "In this case, the fast metabolic characteristics of VEN lead to a high abundance of cytochrome isoenzymes (mainly CYP2D6 and CYP2C19) as well as rapidly accumulated O-desmethylvenlafaxine, which are thought to be involved in VEN-associated liver injury." (PMID 34889278, 2021).
insomnia (1 paper, 2019). A sleep disorder characterized by difficulty in falling asleep and/or remaining asleep. "The number of activation symptoms a patient experienced (insomnia, irritability, hyperactivity, and impulsivity) was related to the CYP2C19 metabolizer status, with slower metabolizers experiencing more activation symptoms than faster metabolizers (p = 0.019)." (PMID 30837874, 2019).
ischemic encephalopathy (1 paper, 2024). "The relationship between CYP2C19 gene polymorphisms and ischemic encephalopathy has been reported." (PMID 39472784, 2024).
Kawasaki disease (1 paper, 2022). A rare inflammatory disease characterized by an acute febrile, systemic, self-limiting, medium-vessel vasculitis primarily affecting children. "CYP2C19 genetic variation and clinical factors have been proved to be related with clopidogrel resistance (CR) in adults, while the presence of CR in children with Kawasaki disease (KD) was seldom reported." (PMID 36072880, 2022).
liver cancer (1 paper, 2021). An epithelial or non-epithelial malignant neoplasm that arises from the liver. "In our analysis, CYP2B6 and CYP2C19 were discovered to be upregulated in HCC, and the roles in the process of liver cancer are required to be further verified." (PMID 34423049, 2021).
liver dysfunction (1 paper, 2023). "The pharmacokinetic information about simeprevir, a CYP2C19 substrate (also a substrate of CYP3A4 and CYP2C8) in liver dysfunction patients is not equivocal." (PMID 36901973, 2023).
liver fibrosis (1 paper, 2025). "Meanwhile, ECM1, TRIB1, and CYP2C19 were downregulated, implicating impaired liver fibrosis regulation, carcinogen metabolism, and potential disruption of key signaling pathways." (PMID 41216224, 2025).
male infertility (1 paper, 2013). The inability of the male to effect fertilization of an ovum after a specified period of unprotected intercourse. "We observed a significant interaction between rs4986894 in CYP2C19 and 4-t-OP on male infertility only among the TC/CC genotype and high 4-t-OP exposure group (Pinter = 8.09×10−7, OR = 17.35, 95%CI = 2.33–129.04)." (PMID 23555028, 2013). "We also found rs4986894 in CYP2C19 combined with 4-t-OP exposure increased the odds of male infertility (Pinter = 8.09×10−7)." (PMID 23555028, 2013). "Thus, we hypothesize that 4-t-OP exposure combined with polymorphisms in CYP2C9, CYP2C19 and/or CYP1A1 may interact to impart increased risk of male infertility." (PMID 23555028, 2013).
manic episodes (1 paper, 2023). "We found slower drug metabolism via CYP2C19 to be associated with a higher rate of manic episodes within 3 months after starting treatment with sertraline and with amitriptyline or clomipramine." (PMID 36333412, 2023).
Neonatal sepsis (1 paper, 2023). Systemic inflammatory response to infection in newborn babies. "In the UK, point of care genomic testing for mtRNR1 has been initiated prior to aminoglycoside use in neonatal sepsis, and NICE is expected to shortly release guidelines recommending CYP2C19 testing to guide choice of therapeutics after stoke." (PMID 37810217, 2023).
neuroblastoma (1 paper, 2023). Neuroblastoma (NB) is the most common solid, extracranial childhood tumor. "In the present study, the contribution of pharmacogenetic variability in CYP2B6 and CYP2C19 to treatment efficacy and cyclophosphamide-induced side effects was evaluated in pediatric patients with neuroblastoma." (PMID 37479763, 2023). "The aim of the study was to reveal the contribution of pharmacogenetic variability in CYP2B6 and CYP2C19 to the treatment efficacy and cyclophosphamide-induced side effects in pediatric neuroblastoma patients under cyclophosphamide therapy (N = 50)." (PMID 37479763, 2023). "Although, neuroblastoma considered to be the most prevalent extracranial solid tumour malignancy in childhood, cyclophosphamide-induced toxicity related to the patients’ CYP2B6 and CYP2C19 status has not been extensively investigated in patients with neuroblastoma." (PMID 37479763, 2023).
Neurodevelopmental delay (1 paper, 2025). "Polymorphisms in CYP3A4, CYP2C19, and CYP1A2 could impair detoxification of environmental toxicants, while dysfunction in CYP2E1 and CYP2D6 has been linked to oxidative stress and mitochondrial impairment—both implicated in neurodevelopmental delays." (PMID 40386062, 2025).
non-small cell lung carcinoma (1 paper, 2014). A group of at least three distinct histological types of lung cancer, including non-small cell squamous cell carcinoma, adenocarcinoma, and large cell carcinoma. "For example, dose escalation of tivantinib, a non-small cell lung cancer therapy, is based on stratification for the CYP2C19 genotype." (PMID 24865298, 2014).
osteosarcoma (1 paper, 2023). A usually aggressive malignant bone-forming mesenchymal neoplasm, predominantly affecting adolescents and young adults. "The clinical relevance of FUBP1 expression in terms of the activation of PTGES and CYP2C19 (a key CYP epoxygenase enzyme in AA metabolism) was further investigated in a group of human osteosarcoma clinical specimens using IHC analysis." (PMID 37180822, 2023). "We found that the expression level of FUBP1 in the clinical osteosarcoma samples was positively correlated with the expression level of PTGES and CYP2C19 (p = 0.002, and p = 0.005)." (PMID 37180822, 2023).
ovarian insufficiency (1 paper, 2016). "Previously, two studies demonstrated that among LN individuals the CYP2C19*2 deficient allele was associated with lower ovarian insufficiency." (PMID 27002825, 2016).
pancreatitis (1 paper, 2025). Inflammation of the pancreas. "Recent studies have suggested that genetic polymorphisms in drug-metabolizing enzymes, particularly cytochrome P450 isoforms such as CYP2D6 and CYP2C19, may significantly influence individual susceptibility to SSRI-induced adverse effects, including pancreatitis." (PMID 41561971, 2025).
poisoning (1 paper, 2014). A condition or physical state produced by the ingestion, injection, inhalation of or exposure to a deleterious agent. "Similar results were found for omeprazole; the pharmacokinetic parameters of omeprazole have almost not changed between control group and acute H2S poisoning group; this shows that the acute H2S poisoning will not induce or inhibit the activity of CYP2C19 enzyme." (PMID 24790991, 2014).
skin reaction (1 paper, 2012). "This could be partly explained by recent reports which showed that NVP was metabolically activated to quinone methidine, a toxic reactive metabolite, by CYP3A4, and, to a lesser extent, CYP2D6, CYP2C19, and CYP2A6, and that this reactive metabolite was responsible for NVP-induced skin reactions." (PMID 22957276, 2012).
somnolence (1 paper, 2020). "Based on the study results, the antidepressant compounds with the highest reporting odds of somnolence and not primarily metabolized by CYP2C19 substrates are: vilazodone, mirtazapine, and duloxetine." (PMID 32201646, 2020). "Further, antidepressants with the lowest reporting odds of somnolence and not primarily metabolized by CYP2C19 are: levomilnacipran, milnacipran, vortioxetine, and buproprion." (PMID 32201646, 2020).
TB meningitis (1 paper, 2023). "Additional induction may also be relevant for orally administered CYP3A substrates with fixed dosing recommendations (e.g., dexamethasone for TB meningitis, where examples for CYP2C19 are lacking)." (PMID 37768317, 2023).
thrombotic disease (1 paper, 2019). The formation of a blood clot in the lumen of a vessel or heart chamber; causes include coagulation disorders and vascular endothelial injury. "Our finding that CYP2C19 expression is reduced with WAA while P2RY1 expression is inversely increased suggests that clopidogrel resistance and susceptibility of AAs to thrombotic disease may be due to ancestry-associated gene expression as an underlying mechanism." (PMID 31798965, 2019).
triple-negative breast carcinoma (1 paper, 2014). An invasive breast carcinoma which is negative for expression of estrogen receptor (ER), progesterone receptor (PR), and human epidermal growth factor receptor 2 (HER2). "As a result, we provide evidence suggestive of the CYP2C19 deletion allele being associated particularly with susceptibility to triple-negative breast cancer." (PMID 25466287, 2014). "However, the deletion in CYP2C19 showed a significant association with triple-negative breast cancer (p = 0.021)." (PMID 25466287, 2014).
tuberculosis (1 paper, 2021). A chronic, recurrent infection caused by the bacterium Mycobacterium tuberculosis. "Patients with tuberculosis with older age and genetic polymorphism of CYP3A4, CYP2C9, and CYP2C19 who received long-term rifampicin treatment were more likely to have antituberculosis drug-induced liver injury." (PMID 34872459, 2021). "We hypothesize tuberculosis patients with genotyping CYP3A4 enzyme, CYP2C9 enzyme, and CYP2C19 enzyme are more likely to have ATB-DILI." (PMID 34872459, 2021).
visceral leishmaniasis (1 paper, 2024). A severe form of leishmaniasis characterized by irregular bouts of fever, substantial weight loss, swelling of the spleen and liver, and anemia (which may be serious). "It was reported that the phenotypic activities of CYP3A4 and CYP2C19 were significantly reduced in Brazilian patients during the acute phase of visceral leishmaniasis." (PMID 38240984, 2024).
cancer (39 papers, 2008 to 2025). A tumor composed of atypical neoplastic, often pleomorphic cells that invade other tissues. "Much more, data show that the polymorphisms of CYP2C19 play a “major role in inter-individual variability in drug response, drug-xenobiotic interactions, and in cancer susceptibility”." (PMID 40331930, 2025). "CYP2C19 polymorphisms have been analyzed about the prostate, bladder, lung, liver, colorectal cancer, and other cancers." (PMID 33192522, 2020). "CYP2C19 polymorphism is considered to be one of the factors that determine an individual’s susceptibility cancer through variations in ability to detoxify carcinogens and/or activate procarcinogens." (PMID 25927305, 2015). "In regard to cancer predisposition, the effect of the CYP2C19 deletion was reminiscent to that of a low-penetrance allele." (PMID 25466287, 2014). "Our meta-analysis suggests that the CYP2C19 PMs genotypes most likely contributes to cancer susceptibility, particularly in the Asian populations." (PMID 24015291, 2013). "More studies should also be carried out to examine the impact of CYP2C19 on cancer risk, especially in Caucasian populations." (PMID 24015291, 2013). "We therefore performed a meta-analysis of the published studies to clarify this inconsistency and to establish a comprehensive picture of the relationship between CYP2C19 and cancer susceptibility." (PMID 24015291, 2013). "This is the first comprehensive meta-analysis that examined the CYP2C19 polymorphisms and the relationship to cancer susceptibility." (PMID 24015291, 2013). "Overall, significant associations were found between CYP2C19 PMs genotypes cancer risk when all studies pooled into the meta-analysis." (PMID 24015291, 2013). "In addition, CYP2D6, CYP3A4, CYP2B6, and CYP2C19 are implicated in anti-cancer metabolism, influencing their efficacy." (PMID 39062040, 2024). "Finally, a total of 30 studies with 11,554 cancer cases and 16,592 controls examining the association between the CYP2C19 polymorphism and cancer risk were included in the current meta-analysis." (PMID 24015291, 2013). "CYP2C19 encodes a member of the cytochrome P450 superfamily of enzymes, which play a central role in activating and detoxifying many carcinogens and endogenous compounds thought to be involved in the development of cancer." (PMID 24015291, 2013). "Therefore, CYP2C19 polymorphism is considered as one of the factors that determine an individual’s cancer susceptibility by the interindividually different ability of detoxification of carcinogen(s) and/or activation of procarcinogen(s)." (PMID 24015291, 2013). "However, several studies conducted among Middle East populations which shown a similar PMs genotypes prevalence as Caucasians found a significant association between CYP2C19 PMs genotype and cancer susceptibility." (PMID 24015291, 2013). "Our results indicated that the PMs genotypes of CYP2C19 is a risk factor for developing cancer." (PMID 24015291, 2013). "In the past decade, two common polymorphisms among CYP2C19 (CYP2C19*2 and CYP2C19*3) that are responsible for the poor metabolizers (PMs) phenotype in humans and cancer susceptibility have been investigated extensively; however, these studies have yielded contradictory results." (PMID 24015291, 2013). "There was preliminary evidence of an association between BMI and CYP2C19 activity in the advanced cancer patients; according to the standard cutoff for BMI, among those with low BMI (<25) 62% (8 of 13) were PM compared with 22% (4 of 18) in patients with a high BMI (>25) (P=0.03)." (PMID 18854824, 2008). "In order to investigate the effects by PPI metabolism in cancer incidence, CYP2C19 genotype was measured in a total of 199 patients." (PMID 34263071, 2021). "In a prospective study of 16 patients with advanced cancer and a CYP2C19 NM genotype, the relationship between the CYP2C19 genotype and phenotype was studied." (PMID 32906709, 2020).
cancer (continued). "In a small study investigating the metabolism of cyclophosphamide in patients with lung, breast and gastrointestinal malignancies, the level of CYP2C19 was lower in patients with cancer compared to the general population." (PMID 31963461, 2020). "Overall, the odds ratio (OR) of cancer was 1.52 [95% confidence interval (CI): 1.23–1.88, P<10-4] for CYP2C19 PMs genotypes." (PMID 24015291, 2013). "The results of this study indicate that the activity of the drug-metabolising enzyme CYP2C19 was compromised in advanced cancer patients." (PMID 18854824, 2008). "In a small study of patients (n=16) with advanced cancer, all individuals had normal CYP2C19 genotype but 25% of these patients were CYP2C19 PM phenocopies." (PMID 18854824, 2008). "A discordance between CYP2C19 genotype and phenotype has been reported previously in a small study (n=16) of advanced cancer patients." (PMID 18854824, 2008). "The activity of the drug-metabolising enzyme CYP2C19 was severely compromised in advanced cancer patients, resulting in a PM status in 37% of the patients who had normal genotype." (PMID 18854824, 2008). "Another possible limitation in our study might the potential effect of CYP2C19 phenoconversion in cancer patients." (PMID 33432065, 2021). "Indeed, CYP2C19 activity was reduced in cancer patients, with a discordance between the measured phenotype and the predicted phenotype from the genotype." (PMID 34867341, 2021). "The mechanism behind the decrease of CYP2C19 activity observed in cancer patients may be related to the inflammatory response even though it remains debated." (PMID 34867341, 2021). "In summary, our meta-analysis demonstrated an association between CYP2C19 polymorphism and cancer risk among Asian populations, but not among Caucasians." (PMID 24015291, 2013). "Secondly, the subgroup meta-analyses considering different type of cancer and CYP2C19 were performed on the basis of a fraction of all the possible data to be pooled, so selection bias may have occurred and our results may be over inflated." (PMID 24015291, 2013). "However, a discordance between CYP2C19 genotype and phenotype has been reported previously in a small study of cancer patients." (PMID 18854824, 2008). "Nevertheless, alternate cytokines or other inflammatory mediators may be involved in the observed decreased CYP2C19 function in advanced cancer." (PMID 18854824, 2008). "Owing to the lack of association between proinflammatory cytokines and CYP2C19 activity in the advanced cancer patients, the samples were also analysed for the levels of growth hormone." (PMID 18854824, 2008). "The implications of compromised CYP2C19 activity are of direct relevance to cancer chemotherapy." (PMID 18854824, 2008). "Therefore, CYP2C19 is considered an important defense against cancer." (PMID 25927305, 2015). "Furthermore, in a majority (7/10) of the deletion carriers with ER negative cancer the second allele was found to be wild type, whereas one (1/10) had a poor-metabolizer CYP2C19*2 allele and the rest (2/10) an ultra-rapid metabolizer CYP2C19*17 allele." (PMID 25466287, 2014). "However, the high incidence of PM in both studies indicates that decreased CYP2C19 activity in cancer patients is a noteworthy effect that could have clinical significance for chemotherapeutics, such as cyclophosphamide, which may be substrates for CYP2C19." (PMID 18854824, 2008). "These qPCR results confirmed a similar distribution of gene expression; overexpression of CYP1B1, CYP7A1, CYP17A1, and CYP19A1, and repression of CYP1A2, CYP2B6, CYP2C19, and CYP26A1 was observed in cancer tissues." (PMID 31258835, 2019). "Amongst the 3 upregulated genes, CYP2C19 and NAT2 have long been reported to participate in the failure of anticancer agents treatment or the increased occurrence of cancers." (PMID 31551763, 2019). "This analysis showed that each of these cancer types has a distinct pattern of expression for CYP1A2, CYP2B6, and CYP2C19." (PMID 31258835, 2019).